SNORD115-32 (small nucleolar RNA, C/D box 115-32)
Synonyms: HBII-52-32
Gene: Small nucleolar RNA gene on chromosome 15 (25,228,967 to 25,229,048, forward strand). Ensembl gene ENSG00000200949.
Gene Ontology:
Biological process: RNA processing
Cellular component: nucleolus
Homologues: Orthologues: rabbit SNORD115 (91% identical), rabbit SNORD115 (90% identical), pig SNORD115 (89% identical), rabbit SNORD115 (89% identical), rabbit SNORD115 (88% identical), rabbit SNORD115 (87% identical), rabbit SNORD115 (85% identical), rabbit SNORD115 (84% identical), pig SNORD115 (83% identical), rabbit SNORD115 (83% identical), rabbit SNORD115 (82% identical), rabbit SNORD115 (80% identical), and 11 more. Paralogues in human: SNORD115-11 (94% identical), SNORD115-29 (94% identical), SNORD115-36 (94% identical), SNORD115-38 (94% identical), SNORD115-43 (94% identical), SNORD115-12 (93% identical), SNORD115-16 (93% identical), SNORD115-22 (93% identical), SNORD115-26 (93% identical), SNORD115-3 (93% identical), SNORD115-39 (93% identical), SNORD115-44 (93% identical), and 37 more.